CXCL11 (C-X-C motif chemokine ligand 11)
Diseases named in the same sentence as CXCL11 in open-access papers (continued):
Sharing a sentence is not in itself a finding about the gene and the disease.
tumor (continued). "However, in another study, CAR T cells constitutively secreting CXCL11 do not increase infiltration of CXCL11-producing, CXCR3+ CAR T cells into the tumor, although they increase the concentration of CXCL11 within tumor stromata." (PMID 36366354, 2022). "Accordingly, we analyse the cytokine expression changes (more than 1.5 log2, 2.8 fold, p < 0.05, t-test) between No take and Take tumours and found a large series of chemokine/cytokine overexpressed in the No take samples, among them IFNG, CXCL13, CXCl9, CXCl11, CXCL10 and CCL5." (PMID 28588211, 2017). "Without exogenous CXCL11 stimulation, blocking endogenous CXCL11 or CXCL12 alone did not influence tumor growth and angiogenesis, whereas the combined inhibition almost completely abrogated tumor angiogenesis, providing evidence for the proposed close relationship of these chemokines." (PMID 26347749, 2015). "The absence of CD14-positive cells within the tumour epithelium in ACP is unexpected as the β-catenin-accumulating epithelial whorls (cell clusters) express a variety of chemo-attractant cytokines (e.g., members of the CCL and CXCL family of chemokines including CCL2, CXCL1, CXCL3, CXCL11)." (PMID 39127699, 2024). "Furthermore, in keeping with the effect of EZH2 inhibition in tumor cells, Mo-TAMs from EPZ-6438-treated MCS showed a consistent enhanced expression of monocyte chemoattractants CCL2 and VEGF but not Th1-recruiting chemokines (CXCL9, CXCL10, CXCL11)." (PMID 33922336, 2021).
infection (182 papers, 2007 to 2026). The state of being infected such as from the introduction of a foreign agent such as serum, vaccine, antigenic substance or organism. "During acute inflammation caused by PCN033 infection, Cxcl9, Cxcl10 and Cxcl11 induction recruits immune cells for PCN033 clearance." (PMID 41295668, 2025). "We also found that STRS led to increased detection of putative protein-coding genes, including Ly6a2, Cxcl11 and Mx2, which were associated with infection." (PMID 36329320, 2023). "Examining the leading-edge subset of these pathways underscored that genes associated with Th17 cells are associated with WT infection while IFNγ-stimulated genes such as CXCL11 are associated with ΔΔstx infection in the lamina propria." (PMID 33529199, 2021). "CXCR3 and its ligands (CXCL9, CXCL10, and CXCL11) are undoubtedly linked to the Th1 pattern and constitute an inflammatory pathway that coordinates the immune responses at sites of infection and inflammation." (PMID 24586509, 2014). "With RANTES, CXCL10, and CXCL11, most of these targets have also been upregulated in apical secretions of primary human Fallopian epithelial cells 48 h post Ct infection; and CXCL10 and CXCL11 have also been associated with the increased risk of Ct reinfection in women." (PMID 34684219, 2021). "Likewise, CXCL9 and CXCL11 have been associated with infections such as rhinovirus and influenza virus." (PMID 30467502, 2018). "The CXCR3 ligands CXCL9, CXCL10, and CXCL11 are potent chemotactic factors for activated T cells, which are highly susceptible to infection in vivo, and these IFN-γ-inducible chemokines are consistently increased in expression in multiple tissues following SIV infection." (PMID 19149556, 2009). "Overall, we found that BST2, ZBP1, CXCL11, and IFITM1 are associated with infection with SARS-CoV-1, SARS-CoV-2 WA-1 and Omicron BA.1, hepatitis C virus, HIV, and influenza virus." (PMID 39874350, 2025). "The recruitment of T cells, natural killer cells, monocytes/macrophages, and monocytes/macrophages at sites of infection is mediated by the protein-coding gene CXCL11." (PMID 40822974, 2025). "The fact that certain cytokines such as CXCL9, IP-10, and CXCL11 remain unchanged in the Delta infection argues against the dampened immune response being solely due to the viral copy number." (PMID 41157615, 2025). "Top downregulated DEGs in bystander cells indicated a decreased enrichment of certain pro-inflammatory cytokines and signaling molecules in ADE compared to conventional infection conditions, including CXCL11, CXCL10, CCL2, DOCK4, STAT1, and JAK2." (PMID 39902963, 2025). "CXCL10 and CXCL11 are proinflammatory chemokines that recruit immune cells, including monocytes and T cells, to the sites of infection or injury." (PMID 38638435, 2024). "Other reports have demonstrated that CXCL9 and CXCL11 chemokines play an important role in the recruitment of T cells to the site of infection during influenza virus infection." (PMID 39066364, 2024). "CXCL10 and CXCL11 highlight the proactive immune response by drawing immune cells to infection or inflammation sites." (PMID 38957806, 2024). "In contrast, secretion of chemokines such as RANTES, MIP-3α (CCL20), MIP-1β (CCL4), and I-TAC (CXCL11) remained unaltered or moderately upregulated in the Usp25−/− cells upon infection." (PMID 37683630, 2023). "Before infection, the latent condition presented the chemokine panel with near-high levels of CXCL11 and mild or moderate levels of CXCL2, CCL4, CCL2, CCL1, and CXCL9." (PMID 37149713, 2023). "In AGM, the expression of Ccl2, Ccl3, Ccl4, Ccl7, and Ccl8 together with Cxcl10 and Cxcl11 also increases during infection, although more rapidly and with a more marked expression in nonpolarized rAM than in hamsters." (PMID 37350967, 2023).
infection (continued). "Hantavirus species comparative studies performed in HUVECs show similar gene expression profiles for CCL5 during HTNV and PHV infection, whereas both CXCL10 and CXCL11 transcript levels are expressed the highest following infection of HTNV followed by PHV." (PMID 37766212, 2023). "The expression level of CXCL11 in the normal group was found to be substantially greater (p < 0.01) than that in the infection group by qPCR assays." (PMID 36356076, 2022). "Although serum CXCL10 and CXCL11 levels were negatively correlated with the potency upon infection, post-vaccination levels tended to be positively correlated in the recovered patient group." (PMID 36366324, 2022). "CXCL10 and CXCL11 are chemokine ligands that recruit the leukocytes which drive the IFNγ-response, including Th1 polarisation, leukocyte activation and suppression of infection-induced genes in the urothelium (reviewed)." (PMID 35194151, 2022). "The results revealed that the 13 detected CpG sites in the CpG island of the CXCL11 promoter region were methylated to varying degrees, and one CpG (mC-7) site had significant differences between the infection and control groups." (PMID 36356076, 2022). "Here, we determined the regulatory mechanism of CXCL11 expression in IPEC-J2 against infection by E. coli F18." (PMID 36356076, 2022). "At week 2 post-infection, expression levels of Cxcl10 and Cxcl11 tended to be higher in vaccinated C57BL/6 and IL-23p19−/− mice and were even significantly increased in vaccinated IL-17A−/− mice when compared to the respective unvaccinated control group." (PMID 34351501, 2021). "While some expression patterns remained elevated during infection, by day 5 there was increased Il-12a, Il-12b, Il-6, Cd80, and Cxcl11 expression that corresponded with elevated Il-15 levels in young adult H1N1 and H3N2 infected lung." (PMID 34829979, 2021). "Changes in one cytokine (interleukin [IL]-6), one cytokine-related protein (IL-1 receptor antagonist [IL-1RA]), and three chemokines (eotaxin, monocyte chemoattractant protein [MCP]-1, and I-TAC [CXCL11]) were observed immediately after infection in most CMs." (PMID 34625475, 2021). "Although C57BL/6 mice have a truncated CXCL11 gene, we observed very similar infection trajectories between C56BL/6 mice and A/JCr mice with only subtle differences between the two inbred backgrounds." (PMID 35186781, 2021). "The CXCL9 network is connected with ascending infection, while the CXCL11 network is distant and disconnected, which indicates a more favorable host response." (PMID 32127796, 2020). "As they have a common receptor (CXCR3), CXCL9, CXCL10, and CXCL11 have generally been studied together, and studies of combinations of CXCL9, CXCL10, and CXCL11 in infection, injury, and immunoinflammatory responses have been conducted." (PMID 31836011, 2019). "Our data demonstrate that CXCL11 is significantly up-regulated during PHI, positively correlating with CXCL9 and CXCL10, and negatively associated with CD4+ T-cell count at 1-year-infection point." (PMID 31836011, 2019). "Among the infection-induced genes, a homolog of the human CXCL11 chemokine gene, cxcl11aa, stood out as the most strongly overexpressed M1 marker." (PMID 31110502, 2019). "CXCL9 and CXCL11 were negatively correlated with CD4+ T-cell count at 1-year-infection point (CXCL9, r = − 0.5692, p = 0.0007; CXCL11, r = − 0.3741, p = 0.0349)." (PMID 31836011, 2019). "The CXCL10 and CXCL11 were significantly induced during L2-MHV3 infection in both WT and IL-33 KO mice with an exacerbated manner especially at 72 h PI in IL-33 KO context." (PMID 28607531, 2017). "Multifunctional Th17 cells (IFN-γ+IL-17A+) co-expressing CXCR3/CCR6 are known to upregulate the ligands for CXCR3 (CXCL9/CXCL10/CXCL11) on the lung parenchymal cells, which helps to recruit Th1 cells to the site of infection." (PMID 28985739, 2017).
infection (continued). "Nonetheless, the absence of IFNγ induction in IL-33 KO and the expressions of CXCL10 and CXCL11 were strongly upregulated during L2-MHV3 infection especially in IL-33 KO background at 72 h PI." (PMID 28607531, 2017). "There was a strong induction of chemotactic factors, including CXCL10 and CXCL11, which are important for recruitment of monocytes/macrophages to the site of infection." (PMID 29051759, 2017). "Among them, CXCL9, CXCL10, and CXCL11 were elevated more significantly following HEP-Flury infection at 4 dpi than CVS-11 infection." (PMID 27242764, 2016). "CXCR3 and its ligands (CXCL9, CXCL10, CXCL11) are thought to govern the recruitment of leukocytes to the sites of inflammation and infection." (PMID 27068264, 2016). "CXCL10 (IP-10) and CXCL11 were two of the cytokines that were expressed in animals that succumb to infection." (PMID 27595844, 2016). "Three notable exceptions were CCL7, CXCL10 and CXCL11, which peaked (respectively) at 42.8, 35.5 and 6.6 times the level of expression at 7 days post-infection compared to the pre-infection levels." (PMID 27595844, 2016). "With increased time of infection, the expression of M1-type molecular markers such as CXCL11 and TNF-α significantly decreased, with the exception of CD86, which showed no significant change." (PMID 26091535, 2015). "At day 9 post challenge, gene expression of IFN-γ and chemokines (e.g. CXCL10, CXCL11) in mock vaccinated guinea pigs, compared to C. caviae EB vaccination or naïve guinea pigs, correlated with active/ongoing infection." (PMID 25502875, 2014). "M1-related chemokines CXCL9, CXCL10, and CXCL11 significantly increased after 3 weeks of infection and then declined." (PMID 24666892, 2014). "Increased expression of CXCL9, CXCL10, and CXCL11 suggests either that IFN-γ induces the expression of these chemokines or that Type I interferons are increased during the first 12 hours of infection in the bovine intestine." (PMID 22096503, 2011). "At eight weeks after infection the expression of the M1 markers iNOS and CXCL11 was significantly increased, and these markers were further upregulated at 26 weeks of infection." (PMID 21124899, 2010). "In unimmunized mice, only the expression of CXCL11 was significantly upregulated four weeks after infection compared to naïve mice." (PMID 21124899, 2010). "During our analysis we found that CXCL10 and CXCL11 were among the most highly induced chemokine genes during infection with both viruses." (PMID 19798428, 2009). "Moreover, STAT1-dependent chemokines including CCL5, CCL8, CXCL10, and CXCL11 showed a slight increase during the early stage of infection, the most significant increase occurred after 10 h.p.i, peaking at 24 h.p.i." (PMID 40934228, 2025). "The most significantly upregulated gene upon PCN033 infection was Cxcl9, followed by Cxcl11." (PMID 41295668, 2025). "CCL5 and CXCL11 recruit T cells and other immune cells to sites of infection." (PMID 41258789, 2025). "Furthermore, PG-1 significantly downregulated key immune-associated genes, Cxcl9, Cxcl11, Tnfrsf9, Vdr and Ramp3, which were among the top 10 significantly upregulated genes post PCN033 infection." (PMID 41295668, 2025). "Measurement of chemokines in the lung showed several alterations in global IFNLR1-/- mice compared to WT mice both during super-infection and single S. aureus infection, including increased TNFα, CXCL11, CXCL12, and MIP3α and decreased IL-1β, MIP1β, and CXCL16." (PMID 39178311, 2024). "Interestingly, POPG failed to inhibit RV-A16 replication even though it attenuated virus-induced IL-6 and CXCL11 secretion at 48 h post-infection." (PMID 36992456, 2023). "We further investigated the possible differences in host defense pathways by RNA-seq analysis and found an increase in some key host defense transcripts, such as IFNL1, IFNL3, CXCL10, and CXCL11, in response to infection with recent EV-D68 isolates compared to Fermon." (PMID 37376591, 2023).
infection (continued). "This study assesses the value of the CXCR3 ligands CXCL9/MIG, CXCL10/IP-10 and CXCL11/I-TAC when used to supplement the standard infection markers C-reactive protein (CRP) and procalcitonin (PCT) in the diagnostic algorithm of neutropenic fever in children with cancer." (PMID 36670590, 2022). "They speculated that the apical release of Ad14p1 might facilitate infection of the lower respiratory tract and that increased expression of IL-6 and IP-10 and CXCL11 might contribute to the increased host inflammatory response." (PMID 32486177, 2020). "Notably, we observed upregulated mRNA expression levels of IFNα/β, IL6, TNF and several chemokines as CXCL10 or CXCL11 after USUV infection." (PMID 28873445, 2017). "Among these genes, several encode chemokines (IL8, CXCL1, CXCL10, CXCL11, CXCL9, PF4, PPBP), a family of small proteins that play important roles in the immune system through leukocyte recruitment, cell communication and cell activation during infection." (PMID 26791855, 2016). "The authors also purified the zebrafish counterparts of the human chemokine (C-X-C motif) ligand 11 (CXCL11) family and demonstrated that two of these are inducible by infection and specifically recruit macrophages via the CXCR3 receptor in the zebrafish model." (PMID 25573892, 2015). "Furthermore, another group reported that the CXCR3 ligands, CXCL9, CXCL10 and CXCL11, were induced markedly at the levels in the spleen, lung, and liver following infection with T. gondii." (PMID 24661782, 2014). "Furthermore, the gene expression of the cytokines Cxcl9, Cxcl10, Cxcl11 and Ccl20 was increased early after infection." (PMID 25137043, 2014). "Most importantly, chemokine genes e.g., Cxcl9, Cxcl10, Cxcl11, Cxcl13, Ccl3, Ccl5 and Ccl12 that exert a chemotactic signal for the immune cell migration to the site of the injury were upregulated at 72 and 96 hr post infection." (PMID 18558011, 2008). "Notably, infection by the Delta variant induced significantly higher levels of chemokine mRNAs such as CXCL9, CXCL10, CXCL11, and CCL2 than infection by the wild type and there was negligeable upregulation of cytokine and chemokine mRNA levels in mice infected with Omicron at 3 dpi." (PMID 38257760, 2023). "Similarly, the consistent overlapping expression of the CXCR3 ligands, Cxcl9, Cxcl10 and Cxcl11 may also be unsurprising as there will be distinct stages of the immune response where CXCR3+ T cells are required to fight infection/disease." (PMID 37934811, 2023). "Interestingly only Mayotte 2008 induced an increased secretion of IFN-β, CXCL9, CXCL10, and CCL5, and only CXCL11 was increased for both RVFV strains infection." (PMID 37306630, 2023). "This highlighted that CXCL10 and CXCL11, chemokines responsible for immune cell recruitment to the site of infection from the bloodstream, were among the core group of 29 DE genes and could be detected at both temperatures, albeit up-regulation was stronger at 37°C compared to 33°C." (PMID 33780434, 2021). "Infection of rhesus (Macaca mulatta) or cynomolgus (Macaca fascicularis) macaques with pathogenic SIV leads to the induction of multiple inflammatory chemokines in lymph nodes and spleen including: CXCL8; CXCL9, CXCL10, and CXCL11; CCL3, CCL4, CCL5; CCL2; CCL19; and CCL20." (PMID 19149556, 2009). "Dynamic infection-responsive genes, including CXCL10, CXCL11 and IL15, exhibited robust antiviral signatures, which highlighted Mac_CD163 as key cellular mediators in the immune response to ASF." (PMID 42216858, 2026). "When examining individual cytokines, the chemokines IP10, CXCL11, and CXCL9 (involved in the recruitment and maturation of the immune response) were upregulated after infection with all strains of SARS-CoV-2 except Delta." (PMID 41157615, 2025). "BST2, ZBP1, CXCL11, and IFITM1 were involved in protein binding, and they are also broadly engaged in biological processes related to IFNs and responding to infections." (PMID 39874350, 2025).